IL10 (interleukin 10)
Diseases named in the same sentence as IL10 in open-access papers (continued):
Sharing a sentence is not in itself a finding about the gene and the disease.
colitis (continued). "Taking advantage of this novel mouse model, we investigated the dynamics of IL-10 afforded protection during DSS-induced colitis." (PMID 29545807, 2018). "We also show the potential of this model for the study of the IL-10 biology in the specific setting of DSS-induced colitis." (PMID 29545807, 2018). "These mice are unable to produce the anti-inflammatory cytokine IL-10, which is essential for the control of immune responses and thus prevents colitis development." (PMID 30410494, 2018). "Six weeks later after the recipient mice developed colitis, we assessed IL-10 production by Th1, Th17, and Treg cells in LP of the inflamed intestines." (PMID 30177845, 2018). "Recently we reported the development of a single-channel NIRF endoscopic system, able to discriminate IL-10 colitis-induced dysplasia from colitis in murine colitis models." (PMID 30388158, 2018). "In the present study, C. glabrata overgrowth reduced IL-10 expression during the development of colitis, while β-glucan treatment increased IL-10 production via PPARγ sensing." (PMID 30524506, 2018). "To confirm that the protective effects of mast cell engraftment were not a result of supplying IL10 derived from engrafted WT BMMCs, we also assessed colitis in DKO mice engrafted with IL10−/− BMMCs (derived from IL10−/− mice)." (PMID 29849494, 2018). "Here, we have examined the relationship between IL-10 and the differentiation of intestinal Mφs in inflammation in more depth by exploring Mφ behavior during colitis induced by inoculation of mice with Helicobacter hepaticus in the absence of IL-10 signaling." (PMID 29203542, 2018). "The central role of increased IL-10 production by SCFA-treated Th1 cells in suppression of Th1-driven intestinal inflammation is further confirmed by the fact that blockade of IL-10 pathway exacerbated colitis induced by butyrate-treated Th1 cells." (PMID 30177845, 2018). "Here, we have explored these ideas using the model of colitis induced by Helicobacter hepaticus in the context of neutralization or deletion of interleukin-10 (IL-10)." (PMID 29203542, 2018). "In this context, and in view of the high expression seen in the SI of induced mice, the pMT-10 mouse model offers an opportunity to further address the effects of IL-10 expression in the gut in the context of colitis." (PMID 29545807, 2018). "Overall, these data indicate that IL-10−/−;T-Hk2−/− develop colitis, but with a lower severity than IL10−/− mice." (PMID 30140438, 2018). "In a mouse model of T cell-induced colitis, GM-CSF increased the production of IL-4, IL-10, and IL-13 and decreased the production of interferon gamma (IFN-γ) in lamina propria mononuclear cells." (PMID 29703251, 2018). "Because the Cx3cr1+/gfp reporter mice are IL-10 sufficient, we had to induce colitis by H. hepaticus inoculation plus weekly administration of anti-IL-10R monoclonal antibody (MAb)." (PMID 29203542, 2018). "Curcumin treatment of in vitro-generated bone marrow-derived DC resulted in the expression of ALDH1 as well as IL-10 and these DC, acting via induction of Tregs and Tr1 cells, inhibited colitis in vivo." (PMID 29774025, 2018). "SCFA-treated Blimp1−/− Th1 cells produce less IL-10 and induce more severe colitis compared to SCFA-treated WT Th1 cells." (PMID 30177845, 2018). "The combination drug modulated the production of both proinflammatory cytokines (IL-6, IL-1β, and IL-17) and an anti-inflammatory cytokine (IL-10) in mice with DSS-induced colitis." (PMID 29466999, 2018). "IL10−/− mice spontaneously develop colitis in a T cell-dependent manner thought to be driven by Th1 and Th17 cytokine-producing cells." (PMID 30140438, 2018). "In summary, our studies revealed that gut microbiota metabolites SCFAs constrain the pathogenic potential of gut microbiota antigen specific Th1 cells to maintain intestinal homeostasis and suppress colitis progression through production of IL-10." (PMID 30177845, 2018).
colitis (continued). "A previous study reported that colonization with a mixture of Clostridium species from clusters IV and XIVa can suppress colitis through the induction of IL-10-producing regulatory T (Treg) cells." (PMID 29988607, 2018). "Colitis in IL10 KO mice is attributed to the increased production of inflammatory mediators such as TNF and IL1b as well as to a hyper-activated Th1 response." (PMID 29985419, 2018). "Although DSS colitis is mainly an innate immunity-driven condition, our study adds to the growing body of evidence showing that Foxp3+ Treg and IL-10 Bregs can suppress a mainly innate-driven inflammation." (PMID 29774025, 2018). "We show that a short period of IL-10 overexpression prior to the induction of colitis ameliorates the disease outcome, despite the presence of CD11b+ Ly6C+ cells in the gut, previously associated with the development of detrimental inflammation." (PMID 29545807, 2018). "Although IL-10 and arginase activities were demonstrated as critical mediators of M2 in colitis, their cellular targets are unclear." (PMID 29774026, 2018). "For example, the genetic deletion of interleukin (IL)-10 or IL-2 precipitated spontaneous colitis in mice, suggesting that these cytokines are essential for colon homeostasis." (PMID 29922293, 2018). "Contrarily, the level of anti-inflammatory cytokine IL-10 decreased (compared to the control group) in the colitis group." (PMID 29724065, 2018). "We then divided the splenic IL-10-producing Foxp3neg CD4+ T cells, which promoted colitis when transferred as one population in Rag1 deficient mice, into CIR rich and CIR poor cells and tested their pathogenicity in vivo." (PMID 30575716, 2018). "Alpinetin (15, 30 mg/kg) significantly up-regulated levels of IL-10 and Foxp3 in colons of colitis mice." (PMID 30166541, 2018). "Administration of Lactobacillus plantarum LP ameliorates the severity of colitis in IL-10-knockout mice." (PMID 29466999, 2018). "More recently, it has been shown that probiotic strains offer the best protection against in vivo colitis in animal models, hence displaying an in vitro potential to induce high levels of IL-10 and low levels of the inflammatory cytokine IL-12." (PMID 30069221, 2018). "IL-10-afforded protection was only seen if IL-10 triggering immediately preceded dextran sulfate sodium (DSS)-induced colitis, thus calling for novel strategies that sustain the effect of IL-10 to offer long-lasting protection." (PMID 29545807, 2018). "Metformin significantly attenuates the severity of colitis in IL-10-/- mice and inhibits the development of colitic cancer in mice." (PMID 29988362, 2018). "With “complete” Ancylostoma caninum (dog hookworm) ESP treatment in TNBS colitis, Nb-EVs promoted the production of IL-10, suggesting a potential mechanism of systemic regulation of inflammation." (PMID 29760697, 2018). "For example, Bacteroides fragilis can secrete capsular polysaccharide A to induce expression of interleukin-10 from regulatory T cells and protect mucous from colitis in a NOD2- and ATG16L1-dependent way." (PMID 29404425, 2018). "Immune cell-produced regulatory factors such as IL-10 and IL-22 promote mucous production and protect from colitis." (PMID 29454391, 2018). "In CD45RBhi T-cell transfer- or 2,4,6-trinitrobenzene sulfonic acid (TNBS)-induced murine models, B. fragilis was shown to protect against the development of colitis by inducing the production of the anti-inflammatory cytokine interleukin-10 (IL-10)." (PMID 30429227, 2018). "In isolated colorectum from DSS-induced colitis mice and IL-10 knockout mice, Erbin expression at both transcriptional and translational levels was markedly decreased compared with that in those control mice." (PMID 29552291, 2018). "To define the role of the mast cell in spontaneous colitis, we examined colonic histopathology in 4 groups of mice on a C57/Bl6 background: wild-type (WT) mice, IL10−/− mice, DKO mice, and DKO mice that were reconstituted with BMMCs." (PMID 29849494, 2018).
colitis (continued). "Transferred splenic B cells from parasite infection mice or enteroantigen-pulsed B cells suppress colitis in an IL-10-dependent manner." (PMID 29784012, 2018). "In the DSS-induced colitis mouse model, B. fragilis inhibits the expression of proinflammatory cytokines IL-6 and TNF-α and enhances the anti-inflammatory IL-10 expression, and thereby ameliorates colitis symptoms." (PMID 30060606, 2018). "In spontaneous colitis induced by IL-10 gene knockout, disruption of PTEN increases the severity of spontaneous colitis." (PMID 29472916, 2018). "The induced M2 macrophages have shown therapeutic potential in chemical-induced colitis, partially by producing IL-10 and arginase-1." (PMID 29774026, 2018). "We have explored the function of pDCs in IBD pathogenesis in mice that lack WASP or IL-10 and consequently spontaneously develop colitis." (PMID 30410494, 2018). "To explore the significance of IL-10 producing Th1 cells in regulation of colitis in vivo, we transferred naïve CBir1 Tg T-cells into Rag−/− mice." (PMID 30177845, 2018). "Polysaccharide A (PSA) from B. fragilis induces the production of interleukin (IL)-10 from immune cells via Toll-like receptor 2 (TLR2) signaling in animal colitis models." (PMID 30065713, 2018). "Activation of the Hh/GLI pathway in the tumor stroma attenuated colitis and limited the colitis-induced adenocarcinoma development by inducing the expression of IL-10, an immune-modulatory cytokine known to suppress inflammatory intestinal damage." (PMID 29695137, 2018). "On the other hand, both EtOH and colitis significantly reduced the levels of mRNA for IL-10 and TGFβ genes." (PMID 30389960, 2018). "Treatment with SCFAs limits colitis induction by promoting IL-10 production, and administration of anti-IL-10R antibody promotes colitis development." (PMID 30177845, 2018). "Compared with WT mice and consistent with previous reports, including our own previous study, of IL10−/− mice on the C57Bl/6 background, IL10−/− mice displayed mild, patchy colitis with incomplete penetrance." (PMID 29849494, 2018). "In our study, less severe colitis induced by SCFA-treated Th1 cells compared to control Th1 cells is in line with the increased IL-10 production by Th1 cells." (PMID 30177845, 2018). "The results from this study highlight a novel protective role for mast cells in a spontaneous, chronic model of colitis, in the IL10−/− mouse." (PMID 29849494, 2018). "For example, it was found that pDCs detect polysaccharide A from Bacteriodes fragilis via TLR2 and induce Tregs, which produce IL-10 leading to protection against trinitrobenzenesulfonic acid (TNBS)-induced colitis." (PMID 29570694, 2018). "It has been recently demonstrated that umbilical cord blood-derived mesenchymal cell extracts reduce experimental colitis in mice through their capacity to stimulate IL-10 production by macrophages." (PMID 29164271, 2018). "In most cases of spontaneous colitis models, including the IL-10−/− mouse, antibiotics or a germ-free state have been shown to prevent the development of colitis." (PMID 30158926, 2018). "As a matter of fact, studies proved that mice deficient in IL-10 spontaneously develop a T-cell-dependent colitis, whereas TGF-β suppresses a T-cell-mediated colitis in animals." (PMID 30138385, 2018). "In conclusion, treatment with the combination of a probiotic complex, prebiotics, rosavin, and zinc attenuated colitis, significantly decreased the levels of proinflammatory cytokines, and significantly increased the levels of Foxp3 and IL-10 in colon tissue." (PMID 29466999, 2018). "Onji and colleagues have reported that carbonic anhydrase I-pulsed bone marrow-derived DC generated in vitro with GM-CSF/IL-10/TGF-β inhibited colitis progression via rebalancing the Foxp3+/TH17 T-cell ratio inside the MLN." (PMID 29774025, 2018).
colitis (continued). "We also assessed IL-10 and Annexin A1 levels, which are known to exert anti-inflammatory roles during colitis, using ELISA and immunohistochemistry, respectively." (PMID 30455703, 2018). "On the other hand, ERCs increased the production of IL-10 and the proportion of CD1d+CD5+ Bregs from colitis mice, an important source of IL-10." (PMID 29784012, 2018). "Our results showed that GABA administration reduced colon levels of inflammatory cytokines such as TNF-α, IFNγ, and IL-12 in DSS-induced colitis mice, while significantly increasing tissue levels of IL-10." (PMID 29867964, 2018). "In both, the Il10−/− model of spontaneous colitis and the DSS-induced model of chronic colitis, fibrosis developed following intestinal inflammation." (PMID 30315190, 2018). "We profiled and identified serum miRNAs that were differentially expressed in the sera of IL10−/− mice during the development of colitis." (PMID 28566745, 2017). "For instance, restraint stress amplifies the severity of colitis in IL-10−/− mice as revealed by histopathology, increased expression of proinflammatory cytokines, and aggravated loss of body weight." (PMID 29213271, 2017). "In il10−/− mice, E. faecalis was shown to be able to promote and perpetuate colitis, to induce dysplasia and rectal carcinoma." (PMID 28632155, 2017). "lactis oral treatment in IL-10−/− mice, revealing the importance of IL-10 in the protection from DSS-induced colitis." (PMID 28194152, 2017). "PCoA yielded a different pattern of clustering between IL10−/− colitic mice (red, D98) and the other models of colitis [orange, DSS treated mice on day 7 (D7); and green, TLR5−/−]." (PMID 28566745, 2017). "Actually, localized delivery of IL-10-secreting Lactococcus lactis ameliorated DSS-induced chronic colitis and the onset of colitis in IL-10-deficient mice." (PMID 28733636, 2017). "C57BL/6 IL-10+/+ and IL-10−/− mice function as C. jejuni colonization and colitis models, respectively." (PMID 28789710, 2017). "It is to be noted that DSS induced-colitis and IL10−/− models represent, respectively, acute and chronic model of intestinal inflammation." (PMID 28566745, 2017). "Recent studies have demonstrated the critical role of TLR/MyD88 in promoting the differentiation of Th1 cells and development of spontaneous colitis in IL-10−/− mice." (PMID 28683149, 2017). "The transferred HD-DCs required IL-4Rα and the capacity to secrete IL-10 to drive IL-4 and IL-10 production and to suppress colitis in recipient mice." (PMID 28094779, 2017). "The loss of IL-10R in tissue-resident macrophages results in spontaneous colitis, highlighting the importance of the macrophage response to IL-10." (PMID 29241040, 2017). "E. faecalis-colonized Il10-/- mice—a model for MIBE leading to colorectal cancer—developed colitis and colorectal cancer after 9 months of colonization." (PMID 29254234, 2017). "Oral administration of L. lactis secreting HSP65 is able to completely prevent DSS-induced colitis in an IL-10/TLR-2-dependent manner." (PMID 29387056, 2017). "Infection with Trichinella spiralis exhibited anti-inflammatory effects in a model of dextran sulfate sodium-induced colitis through activation of local Treg producing IL-10 and TGF-β." (PMID 28603524, 2017). "In another study by Jamontt and colleagues, however, Nod2 was shown to promote IL-10−/− colitis, given that Nod2−/− IL-10−/− mice were protected from colitis development." (PMID 28592996, 2017). "In mice given relatively low concentrations of CMC, low-grade inflammation and obesity/metabolic syndrome was induced in wild-type hosts and promoted robust colitis in IL-10−/− and TLR5−/− mice." (PMID 28507982, 2017). "PLP treatment ameliorated colitis in IL-10−/− mice due to a reduction in colonic TNFα, IL-6, IFNγ, COX-2 and nitric oxide synthase (iNOS) expression and modulation of the chemotactic lipid S1P." (PMID 28804483, 2017).
colitis (continued). "Yet, whereas too little IL-10 leads to spontaneous inflammation and colitis, increased IL-10 production impairs neutrophil recruitment into infected organs and thus decreases GBS clearance." (PMID 29209311, 2017). "Despite the reduction in the macroscopic score when compared with medium or empty vector-harboring L. lactis groups, Hsp65-LL was ineffective in improving the histological score of IL-10−/− mice colitis." (PMID 28194152, 2017). "IL-10- and IL10 receptor-deficient mice spontaneously develop colitis and are widely used murine models of IBD." (PMID 29162986, 2017). "Cystatin from the nematode parasite Ascaris lumbricoides reduces inflammation in a mouse model of DSS-induced colitis by increasing the expression of IL-10, TGFβ with simultaneous reduction of IL-6 and TNFα." (PMID 29141050, 2017). "Chief among these is IL-10; Treg-specific ablation of Il10 is sufficient to induce spontaneous colitis." (PMID 29118930, 2017). "In the case of Lachnospiraceae, a negative correlation has also been shown with disease activity in IL-10 (−/−) murine model of colitis." (PMID 28794801, 2017). "Reduces T-cell-mediated colitis by reducing IFNr and IL-17 in the spleen, mesenteric lymph nodes, and lamina propria, and increasing IL-4 and IL-10." (PMID 29163443, 2017). "In contrast, Fischbeck and colleagues found 4 mg/day of egg SM given via gavage exacerbated colitis and apoptosis in both DSS and IL-10−/− colitis mouse models." (PMID 29143791, 2017). "It was reported that exercise increased IL-10 levels in DSS-induced colitis in adiponectin deficient mice and in TNBS-induced colitis in rats." (PMID 28030847, 2017). "Adoptive transfer of BMDC exposed to helminth homogenates, resulted in CD4+ T cell IL-10 mediated disease suppression in an experimental model of colitis." (PMID 29073139, 2017). "We observed that the expression of IL-10 mRNA in the colons of p85α+/− mice was higher than those of WT mice in both normal and colitis states." (PMID 28733636, 2017). "To confirm the role of IFN-γ in the induction of colitis via CS-stimulated CD4+ T cells, we performed an AT of lung draining lymph node CD4+CD25− T cells from WT or IFN-γ−/− mice to colitis-prone IL-10−/− mice." (PMID 29163466, 2017). "One such therapeutic which has demonstrated considerable potential, and is now in phase 2a clinical trials, is an interleukin-10 secreting L. lactis, which has previously been shown to protect against colitis in a preclinical model of the disease." (PMID 29051554, 2017). "As the expression of the anti-inflammatory cytokine IL-10 is known to have an ameliorating effect on colitis, we also investigated the production of this cytokine by CD4+ T cells." (PMID 28452361, 2017). "In support of this, IL-10−/− mice expressing the human VDR in intestinal epithelial cells resulted in a reduced development of spontaneous colitis." (PMID 28804483, 2017). "Simultaneously, cytokines, including PSMP, IL-6, CCL2, TNF-α, IFN-γ and IL-10 in the colon homogenates were measured with CBA in the time-course study of colitis." (PMID 28698550, 2017). "Continual exposure to gut bacterial antigens was crucial for the induction of CD4+CD62L+GITR+IL-10+ Treg, which exhibited protective behavior in a transfer model of colitis in mice." (PMID 28603524, 2017). "The crucial role of Treg-associated cytokines is supported by the observation that TGF-β1-deficient mice develop multiorgan lymphoproliferative disease of the gut while, IL-10−/− and IL-10R−/− mice develop a spontaneous colitis." (PMID 28302598, 2017). "In order to investigate the Toll-like receptor-2 (TLR2), TLR4, and interleukin 10 (IL-10) molecular signaling pathways involved in BF-mediated prevention of dextran sulfate sodium (DSS)-induced colitis." (PMID 28683149, 2017). "In situ hybridization targeting the GH receptor (GHR) and relevant transcriptional analyses were performed in patients with UC and in IL-10 knock-out mice with piroxicam accelerated colitis (PAC)." (PMID 28946616, 2017).